EFNA1 (ephrin A1)
Diseases named in the same sentence as EFNA1 in open-access papers (continued):
Sharing a sentence is not in itself a finding about the gene and the disease.
cancer (continued). "In terms of this point, Miao and his colleagues reported on the diametrically opposite roles of EphA2 in regulating cell migration and invasion; while activation of EphA2 with ephrin-A1 inhibited migration of cancer cells, EphA2 overexpression promoted migration in a ligand-independent manner." (PMID 24606764, 2014). "Moreover, E-cadherin can promote EphA2 expression and surface localization in epithelial and cancer cells, thereby prolonging EphA2 interaction with ephrin-A1." (PMID 24606764, 2014). "Previous studies on ephrin-A1 in NSCLC have been conflicting, as associations to improved patient outcome have been reported, while upregulation of the ephrin-A1 receptor EphA2 has also been related to poor clinical outcomes in many types of cancer." (PMID 24215488, 2013). "Moreover, the promotion as well as the inhibition of the same signaling pathway by ephrin-A1 was observed in different cells or cancer types." (PMID 24040255, 2013). "In addition, we documented in this study that hypoxia up-regulated a soluble form of ephrin-A1 releasing from cancer cells into extracellular environment." (PMID 24040255, 2013). "A second controversial aspect of EFNA1 signaling in cancer cells is whether the protein promotes or inhibits oncogenesis." (PMID 20979646, 2010). "It will be interesting to determine whether signaling by soluble EFNA1 has any roles during normal development as well as to elucidate further its role in promotion of cancer." (PMID 20979646, 2010). "While some studies underscore EFNA1’s inhibitory effect on proliferation and invasion in malignancies, others emphasize its pro-metastatic tendencies, suggesting a dualistic function that may vary depending on cancer types and specific SE-driven activations." (PMID 39964764, 2025). "The EphA2/ephrin A1 system could be targeted for cancer treatment at least via two mechanisms." (PMID 32811512, 2020). "Thus, it is possible that ephrin-A1 on endothelial cells may mediate cancer cell transendothelial migration through modulation of these adhesion proteins." (PMID 32399207, 2020). "Indeed, stimulation of certain EPHA2 overexpressing cancer cell lines with recombinant EFNA1-Fc fusion proteins has been shown to suppress oncogenesis by causing receptor internalization and in normal epithelial cells EFNA1 functions at cell-adhesions to stabilize E-cadherin adhesion complexes." (PMID 20979646, 2010). "Although EphA2, the primary receptor of Ephrin A1, has been reported to induce EMT of cancer cells, the function of Ephrin A1 in cancer EMT was unconfirmed." (PMID 39838173, 2025). "The dysregulation of cell migration, adhesion and invasion regulators, such as MCAM/CD146, ALCAM/CD166, CAR/CXADR, EFNA1, LAMA5, CD73/NT5E and integrins, contributes to cancer progression and metastasis." (PMID 40314078, 2025). "To further interrupt the cancer-promoting functions of Ephrin A1, we inhibited EGFR activation by EGFR tyrosine kinase inhibitor (TKI) erlotinib and then evaluated the function of Ephrin A1." (PMID 39838173, 2025). "Complementary qRT-PCR analysis demonstrated significant transcriptional upregulation of oncogenic effectors - EFNA1, CXCL8, and PPP1R14A in carcinoma versus control tissues (P<0.05)." (PMID 40406253, 2025). "EFNA1 and MMP13, as secreted proteins, are overexpressed in many cancers, but their expression in normal tissues is very low or undetectable, suggesting their potential as serum diagnostic markers." (PMID 38987376, 2024). "mQTLs of CpG sites cg06639488 (EFNA1), cg12101586 (CYP1A1) and cg14142171 (HLA‐L) was validated by eQTLs at specific cancer tissues, and cg07932199 (ATXN2) provided colocalization evidence of both methylation and susceptibility to multiple cancers." (PMID 37449541, 2023). "Aberrant DNA methylation at several CpG sites related to smoking, including cg06639488 (EFNA1), cg12101586 (CYP1A1), cg14142171 (HLA‐L) and cg07932199 (ATXN2), were indicated with cross‐cancer carcinogenic effects." (PMID 37449541, 2023).
cancer (continued). "In cancer cells, where ADAM17 is highly expressed and active, ADAM17 directly cleaves ephrin-A1 and thereby disrupts EphA2/ephrin-A1 binding." (PMID 36998455, 2023). "A positive correlation was noted between the expression of EFNA1, EFNA3, EFNA4, EFNA5 and CNV in most cancer types; however, EFNA2 expression was only weakly correlated with CNV." (PMID 35945523, 2022). "All other coding genes LPHN2, EFNA1, ISL1, TRIM29, PAWR, and GOSR2 were differentially up- or downregulated in different cancers." (PMID 36352089, 2022). "The results showed that EFNA1 and EFNA4 had the highest expression in pan-cancer, followed by EFNA3 and EFNA5 with high expression, and EFNA2 with low expression." (PMID 35309935, 2022). "In these six cancer-related pathways, four genes (IL8, PRLR, EFNA1, and CHP2) were uniquely regulated by one specific miRNA each (hsa-miR-338-5p_IL8, hsa-miR-338-5p_PRLR, hsa-miR-760_EFNA1, hsa-miR-450b-5p_CHP2)." (PMID 26259570, 2015). "Based on RNA expression data, EFNA1 and EFNA5 were negatively correlated with the stem cell scores in most cancers, whereas EFNA2, EFNA3, and EFNA4 exhibited varying correlations with stem cell scores in different cancers." (PMID 35945523, 2022). "EPHA2 expression has been reported as higher in cancer tissues compared with non-cancerous epithelium, elevated EPHA2 expression being associated with reduced OS, while EPHA2 and ephrin-A1 co-expression are correlated with recurrence rates." (PMID 34445116, 2021). "Eph2 is often overexpressed in human malignant tumors, accompanied by the absence of Ephrin-A1, which can promote tumor invasion and metastasis, induce EMT, and maintain the cancer stem cell characteristics." (PMID 33093441, 2020). "However, ligand-independent signalling in absence of Ephrin A1 has been known to promote oncogenic signalling and migration, establishing the concept of ligand-receptor imbalance in cancer cells." (PMID 36401637, 2023). "We have shown that within a single cancer cell line EFNA1 has both pro and anti-oncogenic properties and that this behavior is influenced by whether EFNA1 is membrane attached or not, and the amount of EFNA1 produced." (PMID 20979646, 2010). "EPHA2/EFNA1 had a positive correlation in PNI and a negative correlation in non-PNI cancer compartments." (PMID 40075699, 2025).
infection (4 papers, 2010 to 2024). The state of being infected such as from the introduction of a foreign agent such as serum, vaccine, antigenic substance or organism. "Transcription of ephrin-A1 and ephrin-A5 ligands was also modulated in splenic T cells isolated from PbA-infected mice at day 5 post-infection prior to their egress from the spleen." (PMID 31999807, 2020). "Additionally, the A-class rodent ephrin ligand (mouse ephrin-A1) supports cell fusion and infection by CedV." (PMID 33809833, 2021). "The up-regulated genes EFNA1 and IL18BP were not significantly modulated in the challenge infection data set." (PMID 20950493, 2010).
neurodegenerative disease (3 papers, 2012 to 2025). A disorder of the central nervous system characterized by gradual and progressive loss of neural tissue and neurologic function. "Further, we plan to transplant NPCs pretreated with ephrin-A1 and PDGF-BB into animal models as a potential treatment for neurodegenerative diseases such as AD." (PMID 32116646, 2020).
adenocarcinoma (2 papers, 2012 to 2014). A common cancer characterized by the presence of malignant glandular cells. "When selecting only the cases with adenocarcinoma histology we found a significant association between ephrin-A1 and osteopontin expression (p = 0.005), but this association was weaker (p = 0.06) when including all patients." (PMID 22853000, 2012). "Moreover, elevated EphA2/ephrin-A1 expression was associated with female gender, reduced smoking status, adenocarcinoma type, well differentiated and p-stage IA NSCLC and EGFR gene mutations." (PMID 24495444, 2014). "Eighteen percent of the adenocarcinomas showed strong positive staining for ephrin-A1, compared to 6% and 4% of the squamous and large cell tumors, respectively (p = 0.004)." (PMID 22853000, 2012). "Expression levels of S100A4 and ephrin-A1 were significantly higher in adenocarcinomas compared to other histological subtypes, and S100A4-positive tumors were smaller and more differentiated than tumors without expression." (PMID 22853000, 2012). "Interestingly, the expression levels of S100A4c, S100A4n and ephrin-A1 were significantly higher in adenocarcinomas compared to the squamous and large cell tumors." (PMID 22853000, 2012). "Interestingly, we found that adenocarcinomas had a higher percentage of S100A4 and ephrin-A1 positivity compared to squamous and large cell tumors, and this finding is in keeping with that of previous studies on S100A4 and ephrin-A1." (PMID 22853000, 2012).
EFNA1 also shares sentences with these, for which no sentence is quoted: Obesity (2 papers); acute lymphoblastic leukaemia (1); age (1); breast invasive carcinoma (1); cataract (1); Cognitive impairment (1); gastritis (1); gastrointestinal tumors (1); infiltrating ductal carcinoma (1); inflammatory bowel disease (1); Kaposi's sarcoma (1); kidney cancer (1); leukemia (1); liver disease (1); metastatic colorectal cancer (1); oral cancer (1); pancreatic tumors (1); Peptic ulcer (1); rheumatoid arthritis (1); Stroke (1); thyroid cancer (1).